TNF (tumor necrosis factor)
Diseases named in the same sentence as TNF in open-access papers (continued):
Sharing a sentence is not in itself a finding about the gene and the disease.
endothelial dysfunction (continued). "We hypothesize that TNFα contributes to endothelial dysfunction and cardiac and vascular injury in deoxycorticosterone acetate (DOCA)/salt-hypertensive mice." (PMID 32190663, 2020). "Besides, it was demonstrated that the high levels of TNF-α induce the production of ROS and lead to endothelial dysfunction in the MetS." (PMID 32188150, 2020). "In vivo studies had shown that the upregulation of TNF-α may contribute to endothelial dysfunction-induced enhanced vasoconstriction by altering the vascular angiotensin II system." (PMID 32426041, 2020). "Besides, endothelial dysfunction and vascular remodeling caused by IL-6, TGF-β, TNF-α, EGFR, and VEGFA are also some of the core features of CVD." (PMID 32454875, 2020). "Endothelial inflammation via TNF-α, IL-1β, or IL-6 pro-inflammatory cytokines favors leukocyte recruitment, endothelial dysfunction and activation of blood coagulation making interleukin-driven proatherothrombotic processes a potential pharmacological target explored in several clinical trials." (PMID 32019950, 2020). "Moreover, our previous study has shown that dihydromyricetin attenuates TNF-alpha-induced endothelial dysfunction through regulating miR-21 in HUVEC cells." (PMID 32913463, 2020). "We found that GlyNAC supplementation significantly improved plasma concentrations of key biomarkers of inflammation (IL-6, TNFα, hsCRP) and endothelial dysfunction (sICAM1, sVCAM1and E-selectin), but accrued benefits receded after stopping GlyNAC supplementation." (PMID 33007928, 2020). "We first established and characterized an in vitro model of endothelial dysfunction by subjecting human umbilical vein endothelial cells (HUVECs) to high glucose (HG, 25 mM D-glucose) and TNFα (5 ng/mL, to mimic inflammation; H + T) for 3 and 7 days (abbreviated as H + T Days 3 and 7)." (PMID 33060583, 2020). "OA may contribute to the pathogenesis of endothelial dysfunction by releasing cytokines including IL-6, by increasing TNFα production, and by inducing apoptosis, necrosis and oxidative stress." (PMID 33003345, 2020). "Furthermore, TNF-α is an important mediator of endothelial dysfunction through the activation of NF-κB and upregulation of NF-κB components." (PMID 33013823, 2020). "NF-κB induces TNF-α signaling to accentuate oxidative stress and endothelial dysfunction induced via an IKKβ-dependent mechanism, which may be associated with inflammatory and insulin signaling pathways seen in T2DM." (PMID 30889182, 2019). "TNF-α has a synergistic effect on monocyte adhesion and endothelial dysfunction." (PMID 31780924, 2019). "The content of the circulating adhesion molecule vCAM-1 was positively correlated with the levels of CRP (r = 0.42), leptin (r = 0.31), TNF-a (r = 0.35) and IL-6 (r = 0.52), indicating the participation of proinflammatory molecules in the formation of endothelial dysfunction (p < 0.05)." (PMID 30871567, 2019). "Interestingly, we demonstrated that resveratrol rescued the TNFα-induced down regulation of GATA2 mRNA expression in our model of endothelial dysfunction." (PMID 30659233, 2019). "Cytokines, including TGF-β1, TNFα, IFNγ, IL-1β, and IL-17A, may regulate blood pressure through effects on endothelial dysfunction, salt and water balance, and sympathetic regulation." (PMID 31572188, 2019). "MPs could represent a link between autoimmunity and endothelial dysfunction by expressing tumor necrosis factor alpha (TNFα), a key cytokine involved in the pathogenesis of RA, altering endothelial apoptosis and autophagy." (PMID 30526655, 2018). "Collectively, these data suggest that DMY attenuates TNF-α-induced endothelial dysfunction maybe through downregulation of miR-21 expression and reduction of ADMA levels, resulting in enhanced eNOS phosphorylation and NO production." (PMID 29682517, 2018).
endothelial dysfunction (continued). "We reveal, for the first time, that SelS could regulate TNF-α-induced endothelial dysfunction, suggesting that SelS might be a new biomarker for preventing vascular inflammatory disease." (PMID 29805311, 2018). "Moreover, interaction between TNF-α and IL-6 also exacerbate oxidative stress and reduce phosphorylation of eNOS, contributing to increase endothelial dysfunction in T2DM patients." (PMID 30170601, 2018). "In addition, NOS inhibitor, L-NAME, also abolished DMY's protective effects on TNFα-induced suppression of cell migration and tubule formation, suggesting that DMY attenuated TNF-α-induced endothelial dysfunction in a NO-dependent manner." (PMID 29682517, 2018). "Indeed, animal and clinical studies have shown that hyperglycemia causes the systemic production of pro-inflammatory cytokines such as TNFα and lL-1β, as well as endothelial dysfunction." (PMID 30158937, 2018). "However melatonin was unable to mitigate the effects of TNF-α induced endothelial dysfunction in primary HUVECs." (PMID 29641523, 2018). "These theories then raise the question of whether the process of endothelial dysfunction and atherosclerosis in RA patients can occur through TNF-α stimulation mechanisms against lipolysis." (PMID 30123370, 2018). "To investigate the protective effect of DMY on TNF-α-induced endothelial dysfunction, we first evaluated whether DMY had cytotoxic effect on HUVECs using CCK-8 assay to assess the cell viability." (PMID 29682517, 2018). "In addition, we demonstrated metformin reduced endothelial dysfunction, significantly reducing TNF-α-induced VCAM-1 expression and enhancing whole-blood vessel vasodilation." (PMID 29466360, 2018). "Thus, the aim of this study is to investigate the potential mechanism behind the attenuating effects of DMY on tumor necrosis factor alpha- (TNF-α-) induced endothelial dysfunction." (PMID 29682517, 2018). "Moreover, increased secretion of adipokines such as proinflammatory cytokines like TNFα, IL-6 and leptin can result in endothelial dysfunction, with the possible involvement of the of kidney vasculature." (PMID 30016369, 2018). "In this study, we used a well-characterised model of TNF-α- induced endothelial dysfunction." (PMID 29466360, 2018). "Moreover, we showed that the new LSM of the modified system was more effective than the traditional system in preventing TNF-α-induced endothelial dysfunction based on qPCR of ICAM-1, HO-1, and PAI-1 gene levels." (PMID 29354066, 2017). "Based on those results, we speculate that nicotine induces endothelial dysfunction at least in part through promoting the macrophage production/release of TNFα in obese rats, which result in disrupting the balance between eNOS and ROS in the endothelium." (PMID 29236702, 2017). "The results of the present study demonstrated that CO and bilirubin could rescue the TNF-α-mediated eNOS downregulation and endothelial dysfunction by inhibiting NF-κB activation and miR-155-5p biogenesis." (PMID 29170479, 2017). "In this report we used 1 ng/ml TNFα to induce endothelial dysfunction." (PMID 28500309, 2017). "Thus, we treated the other strain of HAECs with TNF-α (10 ng/mL) for 6 h as a positive control platform of endothelial dysfunction." (PMID 29354066, 2017). "On this background, we performed a systematic review with meta-analysis to evaluate whether anti-TNF-α biologic treatment has a beneficial effect on endothelial dysfunction in RA patients." (PMID 28706194, 2017). "We administered TNFα to HUVECs to mimic endothelial dysfunction in vitro." (PMID 28500309, 2017). "BACE1 inhibition markedly inhibited TNFα-induced endothelial dysfunction and monocyte adhesion." (PMID 28091531, 2017). "Based on our novel findings of the possible interactive influence between TNF-α and IL-6, we believe that an anti-inflammatory strategy blocking IL-6 and/or TNF-α may effectively prevent T2D-mediated endothelial dysfunction in coronary microcirculation." (PMID 29095915, 2017).
endothelial dysfunction (continued). "Of note however, in that report, resveratrol was used in a preventative fashion administered 2 hours prior to the TNFα insult, whereas in our study, cells were rendered dysfunctional (to mimic the endothelial dysfunction of preeclampsia) before resveratrol was added." (PMID 28500309, 2017). "TNFα may in turn induce endothelial dysfunction via disrupting the balance between vascular eNOS and ROS." (PMID 29236702, 2017). "Taken together, these observations suggest that anti-TNF-α drugs might favourably impact endothelial dysfunction in the middle- to long-term in particular in those patients with relatively preserved endothelial function." (PMID 28706194, 2017). "In summary, our data suggests that there may be an identifiable, beneficial effect of anti-TNF-α therapy on improving endothelial dysfunction in RA patients." (PMID 28706194, 2017). "VE-cadherin protein levels were not affected after TNF-α treatment for 24 h, thus indicating that endothelial dysfunction was not caused by VE-cadherin expression." (PMID 28091531, 2017). "To date, there is no clear evidence that HO-1/CO prevents endothelial dysfunction associated with the downregulation of endothelial NO synthesis in human endothelial cells stimulated with TNF-α." (PMID 29170479, 2017). "This response suggests that TNF-α might also play a role in early endothelial dysfunction following ionizing radiation." (PMID 28209920, 2017). "TNFα is an important inflammatory cytokine released from activated macrophage, T cells, endothelial cells and adipocytes, and has been shown to induce macrophage activation and endothelial dysfunction." (PMID 29236702, 2017). "TNFα is an important mediator and was chosen to model endothelial dysfunction in vitro." (PMID 25575725, 2016). "Therefore, various biomarkers of inflammation, immune activation, and endothelial dysfunction, mainly IL-6, TNF and C-reactive proteine (CRP), have been found related with CVD incidence also in HIV patients." (PMID 27148878, 2016). "However, given that the model induces an inflammatory response with increased levels of the cytokine TNF-α as well as increased plasma levels of markers of endothelial dysfunction, we think that this is unlikely." (PMID 26940500, 2016). "TNF-α is involved in endothelial dysfunction and reduced NO release in obese individuals." (PMID 27562094, 2016). "TNF-α activates also nuclear factor-(NF-)kB which may mediate hypertension and endothelial dysfunction." (PMID 27680100, 2016). "We hypothesize that LDL, oxidized in the artery wall, co-activates macrophages and mast cells, which in its turn leads to the release of TNF-α and histamine that have a sequential and synergistic effect on endothelial dysfunction and monocyte adhesion." (PMID 25811595, 2015). "An increase in TNF-α may contribute to the pathogenesis of dengue diseases by modulating cell death and survival, inflammation, and endothelial dysfunction." (PMID 26199460, 2015). "Hyperglycemia causes release of proinflammatory cytokines (IL-6, IL-8, IL-18, and TNF-α), diminished bioavailability of nitric oxide with attendant endothelial dysfunction, and increased production of oxygen-derived free radicals with enhanced oxidative stress." (PMID 26273664, 2015). "The interactions among KLOTHO, TNFα, NF-kB and inflammatory processes are not restricted to the kidney, with studies suggest that endothelial dysfunction observed in mice deficient in KLOTHO is reversed by KLOTHO reposition." (PMID 25961830, 2015). "Furthermore, as we showed earlier, TNF-α and histamine have a synergistic effect on endothelial dysfunction and monocyte adhesion." (PMID 25811595, 2015). "The adipokines TNF-α and interleukin 6 (IL-6) may furthermore indirectly influence inflammation processes and endothelial dysfunction." (PMID 26580647, 2015).
endothelial dysfunction (continued). "Several reports showed active systemic inflammation may play a role in hypercoagulability, as endothelial dysfunction and inhibition of fibrinolysis which is related to the process of thrombosis can be induced by cytokines such as TNF and IL-1." (PMID 24995324, 2014). "In addition to phagocytosis, macrophages secrete a diversity of cytokines including IL-1β, IL-8, and TNF-α, which lead to endothelial dysfunction." (PMID 24718556, 2014). "On the other hand, the elevated levels of CRP and the pro-inflammatory cytokines, TNF-α and IL-6, reflect the presence of low-grade inflammation in obese subjects with IR that could contribute to endothelial dysfunction." (PMID 24138787, 2013). "This is of potential interest as biomarkers of endothelial dysfunction-endothelial cell activation have been found elevated in patients with RA and anti-TNF-α therapy improved endothelial dysfunction and led to a reduction of the levels of some of these endothelial cell activation biomarkers." (PMID 23431244, 2013). "Also, vessels from subjects with diabetes are characterized by an increased TNF-α production, increased ROS production, and endothelial dysfunction." (PMID 23738043, 2013). "This is of potential interest as biomarkers of endothelial dysfunction-endothelial cell activation are elevated in patients with RA and anti-TNF blockade improved endothelial dysfunction as well as decreased the levels of endothelial cell activation biomarkers." (PMID 23843680, 2013). "Similarly, endothelial dysfunction induced by advanced glycation end products (AGEs) is mediated through elevated TNF-α expression and induction of ROS production with NF-κB functioning as the link between TNF-α and AGEs/RAGE signaling." (PMID 23738043, 2013). "In addition, vascular inflammation plays a critical role in endothelial dysfunction which can be induced by the production of pro-inflammatory cytokines such as tumor necrosis factor-alpha (TNF-α) and interleukin-6 (IL-6)." (PMID 24223557, 2013). "However, concerning serum levels of biomarkers for endothelial dysfunction and inflammation, we found low serum levels of IL-6 and high serum levels of sVCAM-1, TNF-α and hs-CRP in Fabry patients than in healthy volunteers." (PMID 24207059, 2013). "The nearly significant correlation of elevated sCD163 with ADMA and TNF-α in our MS patients could support the view that endothelial dysfunction through mediated TNF-α mechanisms lies behind the reported prolonged PBMC life cycle." (PMID 22558213, 2012). "Cyanidin-3-O-glucoside has been recognized as a potent bioactive molecule that protects against TNF-α–induced endothelial dysfunction, ethanol neurotoxicity in the developing brain, and tumor promoter-induced carcinogenesis and tumor metastasis because of its high antioxidative activity." (PMID 22363605, 2012). "Another possible promoter of endothelial dysfunction in GPA is TNF-α." (PMID 22792461, 2012). "Systemic inflammation, endothelial dysfunction, and high concentrations of interleukin-1β and tumor necrosis factor-alpha (TNF-α) with major impact in the brain (endothelial cells have receptors for these inflammatory mediators) are the norm in exposed children." (PMID 22866040, 2012). "This is of potential irrelevance as biomarkers of endothelial dysfunction endothelial cell activation have been found elevated in patients with RA and anti-TNF blockade improved endothelial dysfunction and also yielded a decrease of the levels of some of these endothelial cell activation biomarkers." (PMID 22910888, 2012). "However, the beneficial effect of the TNF-α antagonist infliximab on endothelial dysfunction seems to be only temporary." (PMID 21696620, 2011). "Moreover, endothelial dysfunction within the coronary microcirculation perpetuates a cycle of inflammation and immune activation, characterized by the release of pro-inflammatory cytokines such as interleukin and tumor necrosis factor-alpha (TNF-α)." (PMID 40243679, 2025).
endothelial dysfunction (continued). "It was demonstrated that the genes associated with TNF-α signaling (TRAF1, TNFAIP2, and NFKBIZ) and oxidative stress regulation (SOD2) were significantly upregulated, suggesting that NS1 activates pathways critical for endothelial dysfunction and vascular inflammation." (PMID 40508120, 2025). "A recent study reported several pathogenic models through which RT may induce cardiac toxicity, including an inflammatory response mediated by pro-inflammatory cytokines, such as tumor necrosis factor-alpha (TNF-α), interleukin-1 (IL-1) and interleukin-6 (IL-6); endothelial dysfunction and fibrosis." (PMID 39469128, 2024). "Similarly, TNFα can lead to endothelial dysfunction, which is related to CKD development." (PMID 38846493, 2024). "Experimental analyses have demonstrated that alterations in neural microcirculation may be mediated by changes in nitric oxide (NO) metabolism and endothelial dysfunction, which are closely correlated with changes in tumor necrosis factor-alpha (TNF-α) and oxidized LDL (oxLDL) levels." (PMID 39769041, 2024). "Elevated TNF-α levels may induce endothelial dysfunction and later AS." (PMID 39598345, 2024). "Interestingly, AMI prevented TNF-α-induced endothelial dysfunction." (PMID 36103099, 2024). "VCAM1 is rarely expressed under physical conditions but could be quickly activated by a pro-inflammatory factor, including TNFα, which regulates the activation, maturation, and cytokine and chemokine release of leukocytes, thus playing a vital and direct role in endothelial dysfunction." (PMID 37841916, 2023). "Previous experimental studies have demonstrated that the levels of IL-12 and TNF-α increase after 30 minutes of ischemia followed by 2 hours of reperfusion in rats, resulting in significant changes in endothelial function and contributing to endothelial dysfunction." (PMID 37305825, 2023). "First, fibrinogen may upregulate the proinflammatory cytokines interleukin-6 and tumor necrosis factor-α, thus exacerbating vascular inflammation and endothelial dysfunction; in turn, this could result in the formation of atherosclerotic plaques and plaque vulnerability." (PMID 37305748, 2023). "Furthermore, the upregulation of cytokines IL-6, IL-1, and tumor necrosis factor (TNF)-α might also trigger endothelial dysfunction and platelet activation to facilitate thrombosis, which could eventually cause myocardial damage." (PMID 37907497, 2023). "Consequently, inflammation-mediated endothelial dysfunction has been observed in aged rat carotid arteries and the adipose tissue of the resistant arteries of diet-induced obese mice, with dysfunction arising downstream of TNF-α elevation." (PMID 37894840, 2023). "Thus, TNF-α-mediated inflammation may have an important role in endothelial dysfunction and body weight increment related to CD consumption." (PMID 35206342, 2022). "Increased levels of TNF-α could increase ROS production, and lead to endothelial dysfunction." (PMID 35463755, 2022). "In addition, UCB and HO-1 simultaneously reduce the increasing tumor necrosis factor-α (TNF-α), nitric oxide (NO), iNOS, endothelial dysfunction, and they block proliferation and migration of the cells via Raf/ERK/MAPK pathway and display anti-inflammatory activity as well." (PMID 35327498, 2022). "Endothelial dysfunction, oxidative stress, VSMCs macrophage foam cells accumulation, toll-like receptor signaling, NLPR-3 inflammasome formation, and subsequent pro-inflammatory cytokine production, such as TNF-α, IL-1β, IL-6 are few of the mechanisms implicated in the atherogenic process." (PMID 35805095, 2022). "Hence, our results indicate that TNF-α inhibition downregulate general vascular inflammatory responses that may contribute to endothelial dysfunction, possibly via the regulation of miRNA-146a-5p." (PMID 35213638, 2022).